TNFAIP8 (TNF alpha induced protein 8)
Diseases named in the same sentence as TNFAIP8 in open-access papers (continued):
Sharing a sentence is not in itself a finding about the gene and the disease.
acute leukemia (1 paper, 2020). A clonal (malignant) hematopoietic disorder with an acute onset, affecting the bone marrow and the peripheral blood. "A previous study has demonstrated high TNFAIP8 expression in acute leukemia cell lines, whereas its exact roles in AML remain understudied." (PMID 32795319, 2020).
acute myocardial infarction (1 paper, 2023). Necrosis of the myocardium, as a result of interruption of the blood supply to the area. "In acute myocardial infarction (AMI), miR-379 binds tumor necrosis factor-α-induced protein 8 (TNFAIP8) and inhibits its activity significantly, leading to the reduce of the level of apoptosis and the inhibition NK-κB signal pathway in H9c2 cells." (PMID 37189131, 2023).
allergic rhinitis (1 paper, 2022). Inflammation of the nasal mucous membranes caused by an IgE-mediated response to external allergens. "Furthermore, the immunomodulatory genes TNFAIP8 and ARHGAP15 were identified in GWAS studies as shared risk variants for several IgE-mediated diseases including asthma, allergic rhinitis and atopic eczema." (PMID 36106020, 2022).
colorectal cancer (1 paper, 2022). A primary or metastatic malignant neoplasm that affects the colon or rectum. "In addition, it was found that miR-539 was low expressed in colorectal cancer, while tumor necrosis factor (TNF)- α Induced protein 8 (TNFAIP8/TIP8) is highly expressed in colorectal cancer." (PMID 36408273, 2022).
diabetic nephropathy (1 paper, 2019). "The study further revealed that TNFAIP8, and not TIPE2 expression, is upregulated in response to high glucose in mesangial cells which leads to increased cell proliferation and up-regulation of NADPH oxidase-mediated signaling pathway, suggesting that TNFAIP8 modulates diabetic nephropathy." (PMID 31723944, 2019). "Moreover, the expression of TNFAIP8 and TIPE2 is associated with diabetic nephropathy in glomeruli from streptozotocin (STZ)-induced diabetic rats, and renal biopsies of diabetic patients in vivo." (PMID 31723944, 2019).
diffuse large B-cell lymphoma (1 paper, 2022). "The protein expression of caspase-8 (which is inhibited by TNFAIP8) was analyzed by immunohistochemistry in a series of 97 cases of diffuse large B-cell lymphoma, and high expression correlated with a favorable overall and progression-free survival." (PMID 36358737, 2022).
experimental autoimmune encephalomyelitis (1 paper, 2020). An autoimmune demyelinating disease of the central nervous system that is produced experimentally in animals by the injection of homogenized brain or spinal cord in Freund's adjuvant. "To determine the roles of TIPE2 and TNFAIP8 in experimental autoimmune encephalomyelitis (EAE), an animal model for MS, we immunized WT, Tipe2–/–, Tnfaip8–/–, and Tipe2–/–Tnfaip8–/–DKO mice with myelin oligodendrocyte glycoprotein (MOG) peptide 35–55, and monitored daily for clinical signs of EAE." (PMID 32313148, 2020).
head and neck cancer (1 paper, 2023). A primary or metastatic malignant neoplasm affecting the head and neck. "A previous research comprehensively assessed the expression and prognosis of TNFAIPs family members in head and neck cancer and found a positive correlation between TNFAIP8 and tumor infiltrating immune cells macrophage, neutrophil, CD8+ T cell, CD4+ T cell, and dendritic cell)." (PMID 37210507, 2023).
Hepatic steatosis (1 paper, 2020). Steatosis is a term used to denote lipid accumulation within hepatocytes. "We demonstrated that higher expression of TNFAIP8 is associated with hepatic steatosis in mice fed EtOH." (PMID 32152268, 2020). "Indeed, our data linked TNFAIP8 to steatotic events in alcohol mediated fatty liver disease development." (PMID 32152268, 2020). "Further, we investigated the association between TNFAIP8/autophagy biomarker LC3B expression and EtOH-mediated hepatic steatosis in vivo using alcoholic C57BL/6J mouse model." (PMID 32152268, 2020). "We also analyzed the association of TNFAIP8 expression and hepatic steatosis in human patients with a history of EtOH use (n = 18) or no history of EtOH use (n = 5)." (PMID 32152268, 2020). "However, this association was not seen in steatotic mouse livers after HFD, suggesting that TNFAIP8 may modulate hepatic steatosis differently in NAFLD and AFLD." (PMID 32152268, 2020).
Insulin resistance (1 paper, 2024). Increased resistance towards insulin, that is, diminished effectiveness of insulin in reducing blood glucose levels. "Our study reveals a sex-dimorphic functional role for TNFAIP8 in adipocytes potentially through the control of PPARG and estrogen that increases insulin resistance and T2D risk, specifically in women." (PMID 39277575, 2024). "Through sex-stratified GWAS, we prioritized TNFAIP8 as a female-specific insulin resistance gene that promotes visceral adipose tissue accumulation at the expense of subcutaneous depots (GFAT and ASAT)." (PMID 39277575, 2024).
leukemia (1 paper, 2020). A malignant (clonal) hematologic disorder, involving hematopoietic stem cells and characterized by the presence of primitive or atypical myeloid or lymphoid cells in the bone marrow and the blood. "To explore the functional significance of TNFAIP8 in leukemia drug resistance, we downregulated TNFAIP8 expression in K562/A02 and HL60/ADR cells by RNAi." (PMID 32795319, 2020). "Notably, the leukemia-promoting action of TNFAIP8 was mediated by sustaining activity of the ERK signaling pathway, through an interaction with Rac family small GTPase 1 (Rac1)." (PMID 32795319, 2020). "In addition, we found that mice bearing AML cells with TNFAIP8 suppression demonstrated lower leukemia infiltration and improved survival, providing in vivo experimental evidence for its therapeutic values." (PMID 32795319, 2020). "In addition, in vivo experiments confirmed that TNFAIP8 suppression lowered leukemia infiltration and improved survival." (PMID 32795319, 2020). "We then evaluated TNFAIP8 expression in leukemia cell lines." (PMID 32795319, 2020). "Finally, by using a murine leukemia model, we found mice bearing murine AML cells with TNFAIP8 inhibition showed improved survival." (PMID 32795319, 2020).
Listeria monocytogenes infection (1 paper, 2018). "Beyond cancer, the biological role of TNFAIP8 in liver infection has been investigated and the study demonstrated that TNFAIP8 regulates Listeria monocytogenes infection by inhibiting Ras-related C3 botulinum toxin substrate 1 (RAC1)." (PMID 30586922, 2018).
liver diseases (1 paper, 2020). "In the current study, we identified a novel role of TNFAIP8 in early development and progression of liver diseases that underlie HCC progression." (PMID 32152268, 2020). "Since these TNFAIP8-induced cellular events all have significance in early liver disease and progression to HCC, targeting TNFAIP8 activity in early liver diseases may provide therapeutic benefit for specific patient populations." (PMID 32152268, 2020).
lymphoma (1 paper, 2025). A malignant (clonal) proliferation of B- lymphocytes or T- lymphocytes which involves the lymph nodes, bone marrow and/or extranodal sites. "In pancreatic ductal adenocarcinoma, increased miR-184 promotes apoptosis via caspase-3/9 activation and Bcl-2 downregulation, while lymphomas show suppression through inhibition of RasL10B, TNFAIP8, and iASPP, promoting apoptosis." (PMID 41379397, 2025).
monocytic leukemia (1 paper, 2018). "TNFAIP8 isoform RNA expression was also evaluated in THP-1 human monocytic leukemia cells and SH-SY5Y human neuroblastoma cells using RT-PCR." (PMID 29928491, 2018).
renal fibrosis (1 paper, 2023). A final common manifestation of a wide variety of chronic kidney diseases characterized by glomerulosclerosis and tubulointerstitial fibrosis. "Time-course study revealed that TNFAIP8 started to increase as early as day 1 in UUO models, and continued to increase along with the progression of renal fibrosis, which was concomitant with CD63 induction." (PMID 37828075, 2023).
skin melanoma (1 paper, 2021). "The potential role of TNFAIP8 in a tumor immune microenvironment in skin cutaneous melanoma (SKCM) has not yet been investigated." (PMID 34925463, 2021).
Streptococcus pneumoniae infection (1 paper, 2021). "We report here that TIPE proteins (TNFAIP8 and TIPE2) protect mice at mucosal sites from local Streptococcus pneumoniae infection by regulating lymphocyte homing, as directed by CCR9." (PMID 34939151, 2021).
viral infections (1 paper, 2019). "Indeed, although TNFAIP8 was initially described as a key regulator of cancer singling and tumorigenesis, recent reports suggest that TNFAIP8 also modulates inflammation, bacterial and viral infections, immune function and homeostasis in several disease conditions." (PMID 31723944, 2019).
tumor (41 papers, 2015 to 2026). "While TNFAIP8L3 in the context of OVCA therapy appears to be associated with antitumor immunity, TNFAIP8 in other cancers exhibits oncogenic properties by inhibiting apoptosis and promoting tumor progression." (PMID 40343258, 2025). "So far, no literature except our team has reported the relationship between TNFAIP8 rs1045242 polymorphism and tumor." (PMID 32821249, 2020). "We first found through bioinformatics analysis that the TNFAIP8 expression level was significantly increased in ccRCC, was positively correlated with tumor stage and grade and was associated with poor prognosis in patients with advanced ccRCC." (PMID 32226521, 2020). "The available lines of evidence reveal TNFAIP8 overexpression in a variety of tumours, and this overexpression is associated with clinical parameters and experimental metastasis." (PMID 30064446, 2018). "In addition, TNFAIP8 rs1045242 polymorphism was also strongly associated with residual tumor, and recurrence, indicating its role of progression in OC." (PMID 32821249, 2020). "The expression levels of TNFAIP8 were significantly associated with tumor status (P<0.05; n=86)." (PMID 25936980, 2015). "Although TNFAIP8 has been detected, whether its expression is associated with tumor invasion remains to be fully elucidated." (PMID 25936980, 2015). "TNFAIP8 functions as a negative regulator of cell apoptosis, playing a crucial role in tumor progression by inhibiting caspase activity and leading to the inactivation of caspase-3 and caspase-8." (PMID 40343258, 2025). "In contrast, factors like ATL3 (Log2 ratio 1.40), ERGIC1 (Log2 ratio 1.64), SPON1 (Log2 ratio 1.25), TNFAIP8 (Log2 ratio 1.99), and VDAC1 (Log2 ratio 1.20), associated with a “highly favorable” prognosis, suggest roles in tumor suppression." (PMID 39858632, 2025). "As a member of the TIPE family proteins, TNFAIP8 has been shown to have an anti-apoptotic and oncogenic potential and promote cell survival and drug resistance, cell proliferation, tumor growth and metastasis." (PMID 37828075, 2023). "We found SKCM patients in the TNFAIP8-high group have a higher percentage of the metastasis tumor type." (PMID 34925463, 2021). "This is in line with the evidence that TNFAIP8 acts as antiapoptotic and pro-oncogenic signaling molecules and plays important roles in oncogenesis and tumor progression." (PMID 34925463, 2021). "Nude mice were inoculated with TNFAIP8 silencing or overexpressing cells to form transplanted tumours." (PMID 33682317, 2021). "Few data further shed light on TNFAIP8 in immune response processes, including an increasing trend of TNFAIP8 mRNA levels in tumor-infiltrating CD4+ CD8+ T cells and the tendency of CD4+ T cells immune function modulation both in mice and humans." (PMID 34925463, 2021). "We found that the mRNA and protein expression of TNFAIP8 were significantly up‐regulated in GC tumour tissues and cells compared with the normal counterparts." (PMID 33682317, 2021). "This study is a pioneer attempt, and further studies of these genes are required to provide a more comprehensive understanding of the potential relationship between the prognosis of TNFAIP8 and the tumor microenvironment." (PMID 34925463, 2021). "We explored the differential expression of TNFAIP8 in tumor and normal tissues in multiple cancer types to evaluate the impacts of TNFAIP8 on different tissues." (PMID 34925463, 2021). "These conclusions suggest the potential role of TNFAIP8 in SKCM tumor development and immune regulation." (PMID 34925463, 2021).
tumor (continued). "Next, we checked the function of TNFAIP8 in ccRCC in the Cancer Genome Atlas (TCGA) database and verified that the relative TNFAIP8 mRNA expression level was significantly increased in tumor tissues compared with that of adjacent tissue." (PMID 32226521, 2020). "The mRNA expression of lncRNA H19 was markedly reduced in tumor-bearing mice after lncRNA H19 or TNFAIP8 knockdown, which likely contributed to its weaker ability to promote tumor growth." (PMID 32514245, 2020). "In HCC cells, expression of TNFAIP8 induces cell proliferation, migration, invasion, and xenograft tumor growth." (PMID 32152268, 2020). "Thirty days after subcutaneous injection, the tumors formed in H19-siRNA and si-TNFAIP8 groups were substantially smaller than those in the negative control group, as evidenced by a dramatic decrease in tumor volume and tumor weight." (PMID 32514245, 2020). "Both lncRNA H19 and TNFAIP8 were significantly up-regulated in tumor tissues from TNBC compared with that in tumor tissues from non-TNBC and adjacent normal tissues." (PMID 32514245, 2020). "Accumulating data indicates that upregulation of TNFAIP8 participated in tumor cell progression, proliferation, invasion, migration, apoptosis, and chemotherapy resistance in different types of tumor." (PMID 31043860, 2019). "In these studies, TNFAIP8 has been shown to be oncogenic and enhance cell proliferation, tumor growth, and metastasis through induction of autophagy and by inhibition of apoptosis." (PMID 31723944, 2019). "Although the combination of cisplatin and control shRNA led to decreased tumour volumes, the combination of A549/TNFAIP8-sh2 and cisplatin led to marked reductions in disease progression." (PMID 30064446, 2018). "The TNFAIP8 protein expression levels were significantly increased in tumour tissues compared with adjacent normal lung tissues (54.1% vs. 24.0%, respectively)." (PMID 30064446, 2018). "In most tumor cells, TNFAIP8 has been reported to have a protective effect; however, TNFAIP8 promotes glucocorticoid-induced apoptosis in thymocytes." (PMID 29928491, 2018). "Our results revealed that TNFAIP8 expression was upregulated in tumour tissues from NSCLC patients and demonstrated that high TNFAIP8 expression is associated with advanced pT stage, advanced pTNM stage and lymph node metastasis." (PMID 30064446, 2018). "Introduction of TNFAIP8 siRNA into OS MG-63 cells showed a reduction in tumor volume and weight of subcutaneous xenografted tumors in nude mice in vivo, suggesting that down-regulation of microRNA-99a and higher expression of TNFAIP8 promotes OS." (PMID 30586922, 2018). "TNFAIP8 protein expression in tumour and normal tissues was then examined through Western blot analyses." (PMID 30064446, 2018). "Consistent with our results, TNFAIP8 also plays a significant tumour-promoting role as an oncogene in various cancer types." (PMID 30064446, 2018). "Tumor necrosis factor-α-inducible protein 8 (TNFAIP8) is a TNF-α inducible anti-apoptotic protein with multiple roles in tumor growth and survival." (PMID 29928491, 2018). "Depletion of TNFAIP8 in tumor cells has been shown to increase expression of genes associated with proliferation suppression, apoptosis, and fatty-acid oxidation genes and to decrease expression of several oncogenes." (PMID 29928491, 2018). "TNFAIP8 protein overexpression is correlated with optimal cytoreduction in EOC, whereas TNFAIP8 mRNA expression is strongly associated with residual tumor size, suggesting that TNFAIP8 overexpression is an independent predictor of platinum resistance in EOC." (PMID 30586922, 2018).